CDKL5 (cyclin dependent kinase like 5)
Diseases named in the same sentence as CDKL5 in open-access papers (continued):
Sharing a sentence is not in itself a finding about the gene and the disease.
neurodevelopmental disorder (50 papers, 2012 to 2025). A behavioral and cognitive disorder with onset during the developmental period that involves impaired or aberrant development of intellectual, motor, or social functions. "Cyclin-dependent kinase-like 5 (CDKL5) deficiency disorder (CDD) is a rare neurodevelopmental disorder caused by mutations in the X-linked CDKL5 gene." (PMID 40332419, 2025). "For example, CDKL5 de novo mutations were found highly enriched in females, even with the similar population rate of X-linked causes of neurodevelopmental disorders in males and females." (PMID 39966983, 2025). "Variants in the X-linked cyclin-dependent kinase-like 5 (CDKL5) gene are associated with a rare neurodevelopmental disorder known as CDKL5 deficiency disorder (CDD)." (PMID 40724873, 2025). "Cyclin-dependent kinase-like 5 (CDKL5) deficiency disorder (CDD) is an X-linked rare neurodevelopmental disorder associated with severe sleep disturbances." (PMID 40332419, 2025). "CDKL5 deficiency disorder (CDD) is a neurodevelopmental disorder caused by mutations in the X-linked cyclin-dependent kinase-like 5 CDKL5 gene." (PMID 38548767, 2024). "Mutations in the X-linked cyclin-dependent kinase-like 5 (CDKL5) gene cause a severe neurodevelopmental disorder (Early Infantile Epileptic Encephalopahty, OMIM 300672), commonly referred to as CDKL5 deficiency disorder (CDD)." (PMID 36613509, 2022). "Herein, we develop a cross-correction-based strategy to enhance the efficiency of a gene therapy for CDKL5 deficiency disorder, a severe neurodevelopmental disorder caused by CDKL5 gene mutations." (PMID 36109452, 2022). "Mutations in the X-linked cyclin-dependent kinase-like 5 (CDKL5) gene cause a rare neurodevelopmental disorder characterized by early-onset seizures and severe cognitive, motor, and visual impairments." (PMID 34073043, 2021). "The neurodevelopmental disorder CDKL5 deficiency is caused by de novo mutations in the CDKL5 gene on the X chromosome." (PMID 31925439, 2020). "CDKL5 has mostly been studied for its role in human neuronal development since mutations in this X-linked gene are associated with neurodevelopmental disorders including early onset seizures." (PMID 32317630, 2020). "CDKL5 disorder is a severe neurodevelopmental disorder caused by mutations in the X-linked CDKL5 (cyclin-dependent kinase-like five) gene." (PMID 29977282, 2018). "Mutations in the Cyclin-dependent kinase-like 5 (CDKL5) gene cause severe neurodevelopmental disorders." (PMID 29702698, 2018). "Since 2003, mutations in the CDKL5 gene have been identified in patients with severe neurodevelopmental disorders characterized by early-onset intractable epilepsy and severe psychomotor retardation." (PMID 29702698, 2018). "The important role of CDKL5 for proper brain function and development elucidate the relationship of CDKL5 mutations with neurodevelopmental disorders." (PMID 25951140, 2015). "The association of CDKL5 with neurodevelopmental disorders and its high expression levels in the maturing brain underscore the importance of this kinase for proper brain development." (PMID 22779007, 2012). "The results of this study confirm that CDKL5 mutations are a potentially important etiological factor in neurodevelopmental disorders." (PMID 22867051, 2012). "Mutations in the cyclin-dependent kinase-like 5 gene (CDKL5) cause a severe neurodevelopmental disorder, yet the impact of truncating mutations remains unclear." (PMID 40042769, 2025). "Additionally, an intron variant in WMI fell within CDKL5, a gene associated with neurodevelopmental disorders such as seizures and autistic-like symptoms." (PMID 34285244, 2021).
neurodevelopmental disorder (continued). "Our findings suggest that the postnatal loss of CDKL5 in forebrain excitatory neurons leads to profound alterations in synaptic structure and function, which could mirror those observed in human neurodevelopmental disorders, particularly CDKL5 deficiency disorder (CDD)." (PMID 40724873, 2025). "Interestingly, CDKL5 is probably the most studied among such “dark kinases” (i.e., poorly understood kinases) mainly due to the relevance of this protein in neuronal development and its involvement in an infantile neurodevelopmental disorder named CDKL5 deficiency disorder (CDD)." (PMID 39201578, 2024). "Here, we focused on CDKL5 Deficiency Disorder (CDD), a severe neurodevelopmental disorder caused by mutations in the X-linked Cyclin-dependent kinase-like 5 (CDKL5) gene." (PMID 36737483, 2024). "Our finding that luteolin treatment ameliorated hippocampal-dependent memory in Cdkl5 +/− mice supports the efficacy of luteolin in the improvement of hippocampal function in neurodevelopmental disorders." (PMID 35955854, 2022). "This protein is encoded by the CDKL5 gene (MIM #300203), known to be implicated in neurodevelopmental disorders with possible regressive features." (PMID 34573171, 2021). "CDKL5 deficiency disorder (CDD) is a complex and severe neurodevelopmental disorder caused by mutations of the CDKL5 gene, for which a cure is not available." (PMID 34073043, 2021). "The relationship between CDKL5 and neurodevelopmental disorders has been the subject of many reports." (PMID 32587608, 2020). "In conclusion, CDKL5 is strongly related to the pathology of neurodevelopmental disorders." (PMID 32587608, 2020). "In view of the positive effects of voluntary running on the brain of mouse models of various human neurodevelopmental disorders, we sought to determine whether voluntary daily running, sustained over a month, could improve brain development and behavioral defects in Cdkl5 KO mice." (PMID 37759796, 2023). "Despite the well-documented evidence of the involvement of neuroinflammatory processes in the pathophysiology of neurodevelopmental disorders, it is not known whether CDKL5-related microglial overactivation plays a role in dendritic pathology and, consequently, in behavioral abnormalities in CDD." (PMID 35955854, 2022).
genetic disorders (9 papers, 2017 to 2025). "CDKL5 deficiency disorder (CDD; MIM:300572, MONDO:0010396) is a rare genetic disease caused by pathogenic variants in the CDKL5 gene (HGNC:11411) coding for cyclin-dependent kinase-like 5 protein." (PMID 39669599, 2024). "For example, querying for ‘CDKL5’ will show 675 genetic variants currently associated with 27 genetic disorders." (PMID 31114901, 2019). "The CDKL5 disorder is a recently identified genetic disorder caused by mutations in the X-linked cyclin-dependent kinase-like 5 (CDKL5) gene." (PMID 28103894, 2017). "CDKL5 deficiency disorder is a rare genetic disease caused by mutations in the CDKL5 gene." (PMID 39049436, 2025).
neurological disorder (7 papers, 2015 to 2024). "We also discuss the relationship between changes in the phosphorylation signalling pathways and the Cdkl5 knockout mouse phenotype and consider future prospects for the treatment of mental and neurological disease associated with CDKL5 mutations." (PMID 32587608, 2020). "CDKL5 deficiency disorder is a rare neurological disorder leading to high morbidity and mortality." (PMID 36274176, 2022). "As CDKL5 plays many important roles in the nervous system, gene mutations leading to the loss of its activity are also believed to lead to the onset of severe neurological diseases." (PMID 32587608, 2020). "Although defects in CDKL5 have mainly been associated with a neurological disease we consider likely that its influence on cell cycle progression may be of relevance also in the pathology." (PMID 28740074, 2017). "Mutations in the X-linked gene cyclin-dependent kinase-like 5 (CDKL5; MIM: 300,203) cause a severe neurological disorder, estimated to affect 1 in 40,000 to 1 in 60,000 live births." (PMID 38877552, 2024). "The identification of new CDKL5 targets that modulate aberrant neuronal activity in CDD will likely have broader implications for other severe neurological disorders." (PMID 35997111, 2022).
cancer (4 papers, 2016 to 2023). A tumor composed of atypical neoplastic, often pleomorphic cells that invade other tissues. "We find that CDKL5 is widely expressed in cancer cell lines, raising the possibility that CDKL5 might regulate SOX9 function in cancer cells." (PMID 32317630, 2020). "In LGG, genes such as CDKL5, KCND1, and DDX3X that have a role in different cancers have differential expression and methylation." (PMID 34621669, 2021). "Our study also raises the possibility that the Cdkl5–Sox9 axis might have important biological functions in other nonrenal cell types, especially neurons and cancer cells." (PMID 32317630, 2020).
infection (3 papers, 2016 to 2024). The state of being infected such as from the introduction of a foreign agent such as serum, vaccine, antigenic substance or organism. "In our animal studies, we demonstrate that CDKL5-KO mice are more susceptible to infection with several genetically diverse viruses compared with their WT littermates." (PMID 37917202, 2024). "Compared with WT mice, CDKL5-KO mice were markedly more susceptible to SINV, HSV-1ΔBBD, and CHIKV infections and succumbed to infection more rapidly than WT mice, suggesting that CDKL5 has a generalized function in host antiviral defense." (PMID 37917202, 2024). "CDKL5, a kinase crucial for neurodevelopment, also regulates virophagy in mouse models by regulating autophagic degradation of viral capsids and limiting infection-induced neuronal cell death." (PMID 37917202, 2024). "Only in the hindbrain did the CDKL5 mRNA reach the levels of wild-type mice, even exceeding them, due to the increased infection efficiency, resulting in a higher number of mRNA-positive cells in this brain region." (PMID 36109452, 2022). "However, using immunofluorescence, we found that cytosolic CDKL5 changed from being diffuse in uninfected HeLa cells to coalescing into punctate structures after infection with SINV." (PMID 37917202, 2024). "In addition to the in vitro findings, we show that CDKL5 is an essential factor in host antiviral defense against diverse viruses by demonstrating that CDKL5-KO mice have enhanced mortality after infection with SINV, CHIKV, and HSV-1." (PMID 37917202, 2024). "As autophagy is critical for host antiviral response and survival during infection with several viruses, we investigated whether CDKL5 is necessary for mouse survival after infection with viruses that are targeted for autophagic degradation." (PMID 37917202, 2024). "WT HeLa cells demonstrated not only higher basal p-T269/S272 p62 compared with CDKL5-KO cells, but also a significantly greater induction of T269/S272 p62 phosphorylation after infection with SINV, which correlated with increasing levels of CDKL5 (compare time = 0)." (PMID 37917202, 2024). "Thus, selective autophagy, mediated in part by CDKL5, is critical for normal human development, neuronal homeostasis, and the protective response to cellular stressors like organellar damage and infection." (PMID 37917202, 2024). "Because autophagy regulates viral antigen clearance, cellular survival, and type I IFN responses, we investigated whether SINV-infected CDKL5-KO mice exhibited defective autophagy at 7 days after infection when differences in response to infection were most apparent between WT and KO mice." (PMID 37917202, 2024). "Additionally, we observed CDKL5 immunoprecipitating with p62 from both the uninfected and infected cell lysates, suggesting that CDKL5 can associate with p62 even in the absence of infection." (PMID 37917202, 2024). "Cdkl5-knockout mice displayed increased viral antigen accumulation and neuronal cell death after SINV infection and enhanced lethality after infection with several neurotropic viruses." (PMID 37917202, 2024). "In contrast, after an 8-hour infection with SINV, p62 from cells expressing WT CDKL5 coimmunoprecipitated a greater amount of ubiquitinated substrate compared with infected cells expressing EV or KD CDKL5-FLAG." (PMID 37917202, 2024). "We inoculated 7-day-old CDKL5-WT and CDKL5-KO mice with SINV, harvested brains from mock-infected and SINV-infected mice 7 days after infection, and assessed autophagy through Western blot analysis." (PMID 37917202, 2024). "Here, we demonstrate that CDKL5 is a key initiator of virus-triggered autophagy and protects neuronal cells in vivo and mice from death during SINV, HSV-1, and chikungunya virus (CHIKV) infections." (PMID 37917202, 2024).
infection (continued). "In uninfected cells, we detected p62 after immunoprecipitation of WT CDKL5-FLAG and to a lesser extent after immunoprecipitation with the KD CDKL5, supporting the finding that CDKL5 interacts with p62 even in the absence of infection." (PMID 37917202, 2024). "In fact, CDKL5-KO cells failed to phosphorylate p62 at T269/S272 after infection." (PMID 37917202, 2024). "The distribution of CDKL5 within these compartments did not change with infection." (PMID 37917202, 2024). "With the same infection efficacy as that of the AAVPHP.B_CDKL5 vector, a gene therapy with AAVPHP.B_Igk-TATk-CDKL5 was sufficient to improve various behavioral defects in the Cdkl5 − /Y mouse, such as innate behaviors and motor performance, and to ameliorate visual function." (PMID 36109452, 2022).
movement disorder (3 papers, 2021 to 2025). Neurological conditions resulting in abnormal voluntary or involuntary movement, which may impact the speed, fluency, quality and ease of movement. "Although the prevalence and characteristics of sleep, behavioral, and movement disorders in CDKL5 have been described in the literature, data on treatment are limited." (PMID 34530725, 2021).
neurodegenerative disease (2 papers, 2022). A disorder of the central nervous system characterized by gradual and progressive loss of neural tissue and neurologic function. "CDKL5 deficiency disorder (CDD) is a severe neurodegenerative disease caused by mutations in cyclin-dependent kinase-like-5 (CDKL5)." (PMID 34913468, 2022). "For example, Cyclin-dependent kinase-like-5 (CDKL5) deficiency disorder (CDD, # 300672) is a severe neurodegenerative disease with early-onset epileptic seizures." (PMID 35625553, 2022).
cardiac disease (1 paper, 2023). "Therefore, oxidative stress, a common pathophysiological factor in cardiac disease, may be the main defect underlying cardiac alterations in the Cdkl5-deficient heart." (PMID 36982627, 2023).
kidney (1 paper, 2025). "A recent study has highlighted the activation of CDKL5 in acute kidney injury, where it contributes to signaling pathways leading to renal tubular epithelial cell dysfunction." (PMID 40903342, 2025).
CDKL5 also shares sentences with these, for which no sentence is quoted: early infantile epileptic encephalopathy (6 papers); Alzheimer disease (3); Lissencephaly (3); Onset (3); Apnea (2); Ataxia (2); bipolar disorder (2); brain disorder (2); Doose syndrome (2); endocrinopathies (2); glioblastoma (2); Landau-Kleffner syndrome (2); Leigh syndrome (2); Macrocephaly (2); Tetralogy of Fallot (2); tumor (2); Aicardi Goutières syndrome (1); Aicardi syndrome (1); Alpers syndrome (1); breast carcinoma (1); Chorea (1); Christianson syndrome (1); colorectal cancer (1); complex partial seizures (1); congenital cataracts (1); congenital central hypoventilation syndrome (1); Cornelia de Lange syndrome (1); Duchenne muscular dystrophy (1); Dyskinesia (1); early-onset epilepsy (1).
A further 51 diseases each share a sentence with CDKL5 in 1 paper.